BDNF (brain derived neurotrophic factor)
Diseases named in the same sentence as BDNF in open-access papers (continued):
Sharing a sentence is not in itself a finding about the gene and the disease.
Obesity (continued). "The BDNF G196A polymorphism in children was only associated with decreased systolic blood pressure (p < 0.05), while the BDNF C270T polymorphism was found not to be related to BDNF levels, obesity, or other parameters after adjusting for potential covariates." (PMID 37007871, 2023). "Therefore, reduced inflammation, increased insulin sensitivity, up-regulated BDNF, and suppressed apoptosis of neurons may be the critical molecular mechanisms for ameliorating obesity-induced cognitive decline during the process of body weight loss." (PMID 35745162, 2022). "Cai and collaborators demonstrated that hyperglycemia and hyperlipidemia induced by obesity might enhance the hippocampal endoplasmic reticulum stress and impair the expression of BDNF and synaptophysin, consequently leading to memory and learning dysfunction in rats." (PMID 36235574, 2022). "Other loci which have been implicated in severe childhood monogenic obesity include genes of the proopiomelanocortin (POMC), the melanocortin receptor 4 (MC4R), the protein convertase 1/3 (PC 1/3), the single-minded homolog 1 (SIM1), and the brain-derived neurotrophic factor (BDNF)." (PMID 36452324, 2022). "The authors’ motivation for this study is that deletion of the BDNF gene in PVH neurons contributes to obesity; thus, they chose to selectively and chemogenetically activate the BDNF gene in PVH neurons to determine whether the opposite effect (weight loss) occurs." (PMID 35338053, 2022). "BDNF may protect against obesity by regulating the metabolism." (PMID 36358820, 2022). "In summary, the effects of obesity-dependent microbiota and its metabolites on neurogenesis and BDNF differ from phylum level to a higher taxonomic resolution, leaving unsolved which and how much SCFAs are beneficial and whether an allocation to a particular bacterial taxon is possible." (PMID 36555576, 2022). "Hence, BDNF might be a neuronal OFF signal that maintains a homeostatic process of neuron–microglia communication in the hypothalamus, while defective BDNF production may ultimately lead to exacerbated microglial activity and obesity." (PMID 34063496, 2021). "In addition, it has been shown that dysfunction of BDNF-TrkB signaling as well as deletion of TrkB receptors from dopamine D1 neurons may result in obesity." (PMID 33367955, 2021). "This study also suggests that patients affected by BDNF deletions have an increased risk for obesity, as 100% were obese by age 10 years compared to 20% without the BDNF deletion, although it also implies that a BDNF deletion alone does not explain the obesity association." (PMID 34970513, 2021). "Thus, both these results and ours provide preliminary evidence in support of the idea that overweight/obesity-related BDNF may play a role in overweight/obesity-related EC." (PMID 33916706, 2021). "However, it might be hypothesized that due to a reduction in BDNF sensitivity in patients suffering from obesity, higher BDNF levels are less likely to prevent food intake, which in turn might be preceded and reinforced by higher visual food cue-reactivity." (PMID 33367955, 2021). "In this regard, the pro-homeostatic effects of grape pomace extract in restoring the basal hypothalamic dopamine and the BDNF levels following the exposure to oxidative stress stimulus support further investigations through in vivo paradigms for confirming the applicability as an anti-obesity agent." (PMID 34684793, 2021). "Therefore, increasing the expression of BDNF may have a favorable effect on improving metabolic function and obesity." (PMID 33868169, 2021). "Disruption of BDNF expression in a patient with a paracentric inversion and deletion of the entire BDNF locus in a mother and child were associated with hyperphagia, severe obesity and mildly impaired cognition with or without attention deficits and hyperactivity." (PMID 30926952, 2020).
Obesity (continued). "However, three genes, i.e., SIM1, BDNF, and tropomyosin-related kinase B (TRKB), when mutated, cause obesity, although the exact mechanisms by which these genetic defects lead to obesity are still unknown." (PMID 33261141, 2020). "Some of the genes associated with monogenetic severe obesity are: leptin (LEP), leptin receptor (LEPR), proopiomelanocortin (POMC), MC4R, preproconvertase 1 (PCSK1), single minded 1 (SIM1), brain-derived neurotrophic factor (BDNF), and tyrosine kinase receptor tropomycin-related kinase B (TrkB)." (PMID 32982666, 2020). "Interestingly, some genes associated with obesity were also associated with AD by different genetic approaches: candidate gene approach FTO, by differentially expressed genes NRXN3, NPC1, NEGR1, or by GWAS approach: LEPR, BDNF, TNFα, and MTCH2." (PMID 32982666, 2020). "Interestingly, the loss of BDNF in diabetic patients is independent of obesity, which indicates two different mechanisms in the regulation of obesity and insulin resistance by BDNF." (PMID 32272767, 2020). "Furthermore, BDNF could be used as a monitoring marker for assessing the process of obesity and the step of visceral adiposity." (PMID 33375318, 2020). "The purpose of this study is to evaluate effects of obesity-induced neurodegenerative disorder prevention by analyzing the effects of long-term lithium and low intensity endurance exercise on the expression of BDNF and GSK3β in the hippocampus of high-fat diet-induced obese rats." (PMID 32397675, 2020). "Interestingly, BDNF heterozygous knockout (KO) mice present hyperphagia and obesity." (PMID 31457016, 2019). "The aim of this study was to investigate the effect of H. erinaceus supplementation on mood disorders and its relationship with pro-BDNF and BDNF circulating levels in subjects affected by overweight or obesity to test whether the two isoforms could be potential biomarkers in clinical studies." (PMID 31118969, 2019). "Moreover, lower BDNF levels are involved with obesity and diabetic complications." (PMID 31736870, 2019). "In addition, BDNF is known to be beneficial in obesity and has anti-diabetic actions." (PMID 31823816, 2019). "However, these factors and variables did not influence the association between BDNF levels and obesity previously observed." (PMID 30081509, 2018). "Therefore, interventions that increase BDNF expression may have favorable effects on metabolic function while improving neurocognitive outcomes in youth with obesity and/or T2D." (PMID 30363954, 2018). "Notably, it was reported that a high-fat diet reduces BDNF expression in the hippocampus, suggesting that the impact of obesity may block the beneficial influence of estrogen on restoration of BDNF." (PMID 30589890, 2018). "Since low BDNF is related to obesity, rTMS may reduce food consumption through increasing BDNF." (PMID 30555295, 2018). "Therefore, enhancing BDNF expression in the hypothalamus by promoting fat browning-related gene expression in subcutaneous fat may represent a potential mechanism by which obesity-related metabolic disorders could be improved." (PMID 28934139, 2017). "Among the six leptin-associated loci, three genes (MC4R, BDNF, and PCSK1) are known to be involved in the hypothalamic leptin–melanocortin pathway, thus it is not surprising that those three loci are found to be associated with obesity-related traits and leptin levels in our pediatric setting." (PMID 29212175, 2017). "Besides the effects on obesity, BDNF prevents the development of T2DM in prediabetic db/db mice." (PMID 29062839, 2017). "Evidence from our previous study suggested that two SNPs (rs17782313 near the melanocortin-4 receptor (MC4R) gene and rs6265 near the brain-derived neurotrophic factor (BDNF) gene) were significantly associated with BMI and obesity, but the molecular mechanisms are not understood." (PMID 28396685, 2017).
Obesity (continued). "Thus, we aimed to evaluate whether low BDNF levels could contribute to the pathogenesis of hyperphagia and obesity in PWS." (PMID 27685845, 2016). "Interestingly, other variants also known to influence reward/addiction associated processes or eating related behaviour such as OPRD1, BDNF, GHRL and CNR1, also revealed evidence of being associated with overweight/obesity or development to an adverse metabolic status." (PMID 26445370, 2015). "RAI1’s regulation of BDNF in the hypothalamus may contribute to the hyperphagia and obesity seen in Smith–Magenis syndrome and haploinsufficiency of RAI1 results in abnormal expression of a number of genes associated with obesity, including proopiomelanocortin (POMC)." (PMID 24519454, 2015). "BDNF may have a protective role against the progression of obesity." (PMID 25309465, 2014). "Moreover, evaluation of curcumin’s effect in the hippocampus and frontal cortex of diabetic db/db mice and in the sera of obese humans, showed that curcumin decreases obesity-induced protein oxidation in humans and restores brain-derived neurotrophic factor (BDNF) levels in mice." (PMID 24945581, 2014). "Other effects of exercise that may affect obesity beyond energy expenditure include: 1) increased brain BDNF levels, 2) decreasing plasma and pancreatic β-cell content of IL-6 and TNF-α, 3) increasing parasympathetic tone, and 4) anti-inflammatory effects of exercise." (PMID 22808000, 2012). "In addition, heterozygous BDNF mice exhibit progressive obesity." (PMID 22768299, 2012). "In addition, BDNF levels are low in obesity and independently so in patients with type 2 diabetes." (PMID 22474595, 2012). "Similarly, BDNF rs925946 associated with overweight, with an OR of 1.20 (1.12–1.29, p = 1.4×10−7), and obesity with an OR of 1.15 (1.06–1.24, p = 3.9×10−4) but not with morbid obesity." (PMID 21912638, 2011). "rs988712*G, which is located 113,058 base pairs downstream of the established obesity locus BDNF on chromosome 11, showed consistent effect direction and was significantly associated with obesity in the French cohort 5 (P = 0.0020), but not in the German cohort 6 (P = 0.135)." (PMID 21708048, 2011). "However, the associations of KCNMA1 and BDNF with childhood obesity are less evident and need to be comfirmed in additional cohorts; with both genes being associated with obesity in French but not in German children." (PMID 21708048, 2011). "Conversely, our study found an association of SGA with the low risk alleles for obesity in the BDNF and SEC16B genes suggesting that these alleles may confer a propensity to small size beginning in-utero, since the same SNP in BDNF has been associated with thinness in women." (PMID 20712903, 2010). "The augmentation in the hippocampus BDNF by adipose CX3CL1 is actively working in young individuals, but it is reduced in aged individuals and in obesity conditions." (PMID 40724847, 2025). "Moreover, alterations in BDNF levels as a function of the Val66met polymorphism have also been implicated in appetite regulation and food intake, eating disorders, obesity, and metabolic disorders, providing evidence that BDNF might play an important role in the pathophysiology of these conditions." (PMID 38997217, 2024). "SH2B1 directly enhances BDNF signaling in PVHSH2B1 neurons, thereby increasing the ability of the PVHSH2B1→DRN neurocircuit to defend against energy imbalance, obesity, and metabolic disease." (PMID 38885417, 2024). "This 12-week study investigates the effects of resistance training with different set structures on the plasma levels of brain-derived neurotrophic factor (BDNF), nerve growth factor (NGF), and obesity-related markers in middle-aged Korean women with obesity." (PMID 37176576, 2023). "We investigated the effects of a 12-week resistance exercise program with different set structures on the blood levels of BDNF, NGF, and obesity-related markers in middle-aged women with obesity." (PMID 37176576, 2023).
Obesity (continued). "In this study, we investigated the effects of different set structures of resistance exercise on BDNF and NGF blood levels in middle-aged Korean women with obesity." (PMID 37176576, 2023). "Few studies have investigated the effects of resistance training with different set structures on BDNF, NGF, adiponectin, leptin, and GLP-1 blood levels in middle-aged women with obesity." (PMID 37176576, 2023). "Large-scale genome-wide association studies have shown that genetic variations in BMI-related genes, such as FTO, BDNF, and MC4R, are closely related to obesity." (PMID 37683016, 2023). "Other mutations within the leptin–melanocortin pathway, such as in proopiomelanocortin (POMC), melanocortin receptor 4 (MC4R), brain-derived neurotrophic factor (BDNF), and the tyrosine kinase receptor B (NTRK2) genes, can also contribute to obesity." (PMID 37762850, 2023). "Most of them have a deletion in the BDNF gene (brain-derived neurotrophic factor) (OMIM*113505), suggesting that obesity phenotype is due to the alteration in this gene." (PMID 37375686, 2023). "To date, this is the first study investigating hypothalamic BDNF-TrkB signaling pathways and their impact on metabolism and behavior in the BTBR mouse model of ASD or in a diet-induced obesity BTBR model." (PMID 36893171, 2023). "The SF-1 neurons release brain-derived neurotrophic factor (BDNF), selective deletion of BDNF in the VMH results in hyperphagia and obesity in mice." (PMID 38027481, 2023). "The rationale for assessing BDNF and NGF levels was to investigate the effects of resistance training on neurotrophic factors in middle-aged women with obesity." (PMID 37176576, 2023). "The current study was designed to evaluate the neurotrophic proteins BDNF and NGF as the salivary marker of obesity in children." (PMID 35626286, 2022). "We will carry out a randomized clinical trial for 8 weeks to evaluate the effect of a TRF on anthropometric measures, eating behavior, stress level, serum BDNF and LBP levels in women with overweight/obesity and food addiction." (PMID 35689257, 2022). "The results show that BDNF and NGF concentrations were significantly increased in OB children compared with NW children, which correlates with obesity measures, indicating a correlation between neurotrophic proteins and fat mass." (PMID 35626286, 2022). "Learning and memory, brain-derived neurotrophic factor (BDNF), obesity, D-galactose, and epigenetics were among the emerging keywords in the experimental studies cluster." (PMID 35572132, 2022). "The present study demonstrated that fractalkine suppresses food intake via activation of the BDNF-TrkB pathway and that reduction of fractalkine-CX3CR1 signalling exacerbates HFD-induced hypothalamic inflammation and accelerates obesity in HFD-fed mice." (PMID 35871167, 2022). "Statistical analysis was performed to analyze the best fit diagnostic value for biomarkers and the relationship of the neurotrophic levels of BDNF and NGF with obesity measures and blood pressure." (PMID 35626286, 2022). "So, the aim of this study is to investigate the effect of TRF on anthropometric measures, eating behavior, stress, and serum levels of BDNF and LBP in women with overweight/obesity and food addiction." (PMID 35689257, 2022). "The receiver-operating characteristics curve of BDNF and NGF is a good marker of obesity and metabolic complications with high sensitivity and specificity." (PMID 35626286, 2022). "So, this study will aim to evaluate the effect of TRF on anthropometric measures, eating behavior, stress, and serum BDNF and LBP levels in women with overweight/obesity and food addiction." (PMID 35689257, 2022). "On the other hand, the deletion of the BDNF gene in the VMH results in an increase in food intake and culminates in obesity." (PMID 33868169, 2021). "In mice, the ablation of BDNF results in deficits of BAT-mediated thermogenesis, impairments of the body temperature in response to cold, and finally, in obesity." (PMID 34833132, 2021).
Obesity (continued). "The role of BDNF gene in relation to WAGR and obesity was supported in a study evaluating 33 patients affected by WAGR syndrome." (PMID 34970513, 2021). "In this study, we observed that maternal HFD/obesity decreased adiponectin, pAKT, SIRT1, and BDNF in rat fetal brain, and maternal resveratrol treatment was able to restore adiponectin, pAKT, and BDNF in male fetal brain." (PMID 32408716, 2020). "Likewise, there is no clear indication whether the changes in BDNF and kynurenate levels are a contributing cause or a consequence of obesity, whether they are of clinical significance, and whether the microbiome has any impact on them." (PMID 32226399, 2020). "Recent advances suggest that obesity and HFD feeding deteriorates cognitive function via abnormalities of BDNF levels." (PMID 32681810, 2020). "In this study, we found that maternal HFD/obesity decreased adiponectin, pAKT, SIRT1, and BDNF in the adult male offspring dorsal hippocampus." (PMID 32408716, 2020). "Our results demonstrate that adiponectin and BDNF play an important role in regulating fat mass and the expression of fat-browning markers in different ways, and also suggest that circulating adiponectin may be used as an important monitoring index for obesity status." (PMID 33375318, 2020). "Among all neurotrophic factors, brain-derived neurotrophic factor (BDNF) and fibroblast growth factor 21 (FGF21) are most relevant to obesity, T2DM, and metabolic diseases." (PMID 32210348, 2020). "Pathway analysis interaction for TAPBP, BDNF, and SORBS2 confirmed the relation of these genes in both obesity and mood disorders." (PMID 32942585, 2020). "SST and leptin exert opposing effect on appetite in contrast to reciprocal roles between leptin and BDNF in hypothalamus, indicating indirect relation between SST and BDNF in regulation of eating behaviour and obesity." (PMID 32272767, 2020). "Maternal HFD/obesity decreased adiponectin, phosphorylation alpha serine/threonine-protein kinase (pAKT), sirtuin 1 (SIRT1), and brain-derived neurotrophic factor (BDNF) in rat placenta, male fetal brain, and adult male offspring dorsal hippocampus." (PMID 32408716, 2020). "However, the association between circulating levels of BDNF and obesity is still not defined." (PMID 30081509, 2018). "In summary, in our sample of Chinese children, we replicated eight adult East Asian obesity-related loci (in/near FTO, MC4R, GNPDA2, PCSK1, SEC16B, MAP2K5, ITIH4 and BDNF) in the same direction of effect as previous reports in adults." (PMID 29212175, 2017). "BDNF is an important downstream mediator of MC4-R signaling, and its administration regulates the obesity in MC4-R knockout mice." (PMID 29062839, 2017). "Therefore, the aim of the present study was to determine whether phyllodulcin could be beneficial for hyperglycemia and dyslipidemia by activating fat browning-related genes of subcutaneous fat and regulating BDNF signaling in the hypothalamus in a mouse model of high-fat diet (HFD)-induced obesity." (PMID 28934139, 2017). "In the present study, the low peripheral BDNF levels in PWS and baseline BDNF’s ability to predict postprandial hunger also support the hypothesis of reduced central BDNF action leading to a lack of satiety and a predisposition to obesity." (PMID 27685845, 2016). "Because BDNF has anti-obesity activity by suppressing food intake, we thus initiated a test to see if 7,8-DHF can be used to prevent the development of obesity." (PMID 26740873, 2016). "Since BDNF knockout in medial basal hypothalamus containing VMH induced hyperphagia and obesity, the BDNF neurons in this region is thought to be critical for regulating energy metabolism." (PMID 24106476, 2013). "In rodents, models of brain-derived neurotrophic factor (BDNF) disruption all exhibited increased food intake, obesity, and hyperphagia, whereas calorie restriction in heterozygous BDNF+/− mice can increase expression of BDNF and reduce obesity." (PMID 23967328, 2013).